BCL2 (BCL2 apoptosis regulator)
Diseases named in the same sentence as BCL2 in open-access papers (continued):
Sharing a sentence is not in itself a finding about the gene and the disease.
cancer (continued). "STAT3 regulated cell survival by inducing Bcl-2 and Bcl-XL to repress apoptosis; thus degradation and inhibition of STAT3 increased apoptosis in several cancer cells." (PMID 30046347, 2018). "In both (SH-SY5Y and U87MG) cancer cells, HBITC affects a decrease in mitochondrial membrane potential and number of cells with activated Bcl-2 protein (inactivation of Bcl-2 protein via HBITC induced S-sulfuration or oxidative stress)." (PMID 29508061, 2018). "Moreover, the lack of evidence for increased risk of cancer or poorer malignancy prognosis among lithium-treated subjects is counterintuitive with the anti-apoptotic consequence of increased BCL2 expression and with the positive correlation between malignancy and BCL2 expression." (PMID 29686228, 2018). "Selective targeting of MCL-1 (A1210477), BCL-2 (ABT-199), and BCL-xL (WEHI-539) revealed that hyperosmotic stress apparently enforced BCL-xL addiction of cancer cells to survive." (PMID 29706657, 2018). "To probe if the anti-cancer effect originates from RT-RDT damage to mitochondria, we detected Bcl-2 and caspase-3 protein expression levels 8 h after X-ray irradiation." (PMID 30333489, 2018). "The present study demonstrates that ZEB2 induces expression of Sp1-regulated genes such as survivin, bcl-2, cyclin D1, and VEGF by cooperating with Sp1 to promote cancer cell survival and endothelial cell activation directly during metastasis." (PMID 29416649, 2018). "The rationale behind choosing Bcl‐2 for prolonging ASC survival, therefore, represents harnessing a desirable characteristic from a cancer disease model." (PMID 28170185, 2017). "BIRD-2 by itself is sufficient to kill Bcl-2-dependent CLL and DLBCL cancer cells by provoking spontaneous, pro-apoptotic Ca2+ signals." (PMID 29340082, 2017). "Therefore, the binding of Bcl-2 to IP3R2 may allow cancer cells to escape cellular senescence." (PMID 29340082, 2017). "We report for the first time that Derlin-1 contribute to the chemoresistance of cancer cells by activation of AKT signaling, with subsequent downstream Bcl-2 elevation." (PMID 28178653, 2017). "Effect of compounds 5e and 10g on active caspase-9 and -3 levels, and the expression levels of Bcl-2 and Bax in MDA-MB-231 cancer cells treated with the compounds at their IC50 concentrations." (PMID 28173708, 2017). "Potent and selective small-molecule MCL-1 inhibitors A-1210477 synergizes with the BCL-2 and BCL-xL inhibitor ABT-263 to kill a variety of cancer cell lines." (PMID 28659182, 2017). "Our data show that the expression levels of Bcl-2 significantly reduced in response to ETBO treatment, implying the significance of Bcl-2 proteins for cancer cell survival." (PMID 29191192, 2017). "Interestingly, for treating cancer cells with upregulated Bcl-2 levels, which display reduced responses to chemotherapy/BH3 mimetics, Bcl-2’s function may be used in an alternative way, namely at the endoplasmic reticulum (ER), the main intracellular Ca2+-storage organelle." (PMID 29340082, 2017). "For example, for the two miRNA pairs that both are members of the miR-15 family (miR-15a/b), the top three possible co-functional targets for the non-cancer diseases are IFNG, MTHFR, RARB, while for cancers are BCL2, CDKN1A and CCND1." (PMID 28340554, 2017). "Binding of Chelerythrine with BCL2, VEGFA and KRAS genes involved in evasion, angiogenesis and self sufficiency of cancer cells provides a new insight for the development of future therapeutics against cancer." (PMID 28102286, 2017). "STAT3 is a transcription factor that participates in tumorigenesis by upregulating expression of cancer promoting genes such as anti-apoptotic BCL2-family members (Mcl-1, Bcl-2, Bcl-XL) and cell cycle regulators (c-Myc, Cyclin D1)." (PMID 29228628, 2017).
cancer (continued). "ATF5 also promotes survival of malignant cells by stimulating expression of anti-apoptotic B-cell leukemia-2 (BCL2) and myeloid cell leukemia sequence-1 (MCL1), a BCL2 family member, indicating a prosurvival role in cancer." (PMID 28860159, 2017). "The methanol extracts of HD can suppress cancer cell proliferation and induce apoptosis, which involve many tumor-related genes and proteins (e.g. TNF-α, IL-1, NF-κB, Fas, AP-1, Bcl-2, Bcl-xL)." (PMID 28702078, 2017). "In the present study, MA was proved to induce cell autophagy by disrupting the combination of Bcl2 and Beclin1 in rat PC12 cells, suggesting a novel molecular target of MA in cancer therapy." (PMID 29088805, 2017). "A collection of cancer cell lines mainly composed of germinal center DLBCL cells, which are highly dependent on Bcl-2 to survive the continuous and permanent death signaling, was used in the present study." (PMID 29340082, 2017). "As such, miR‐15b has been reported to regulate Wee1, Bcl‐2, cyclin E, cyclin D and/or IGF‐1R expression in several types of cancer, and many of these genes also play important roles in drug resistance and apoptosis resistance." (PMID 28145098, 2017). "Cancer cells have developed several ways to modulate IP3R-mediated Ca2+ release, among which Bcl-2-dependent regulation." (PMID 28516063, 2017). "The multiple mechanisms involved in cell proliferation (Cyclin D1, c-Myc), cell survival (Bcl-2, Bcl-xL), and apoptosis (caspase -8, 3, and 9) may mediate the permissive chemotherapy and chemopreventive effects for a selective targeting of highly proliferating cancer cells over normal cells." (PMID 29029547, 2017). "Particular GFRN members can upregulate anti-apoptotic proteins such as BCL-2, BCL-XL, and MCL-1 and downregulate pro-apoptotic proteins such as BAD, BAX, and BIM, all of which contribute to apoptosis evasion and resistance to cancer treatments in patients." (PMID 28446242, 2017). "Most targeted cancer therapies are based on stimulating the expression of BAX protein and/or suppressing BCL-2 protein." (PMID 29340085, 2017). "It has previously been shown that B7-H3 regulates the expression of Bcl-2, Bcl-xL, and Bax via the JAK2/STAT3 signaling pathway to increase the anti-apoptotic ability of cancer cells." (PMID 29088829, 2017). "Camptothecin amplified the effects seen in cancer (CHECK2, BCL-2 and IL8), but opposed them for CYP51A1, ITGA2, DHCR7 or HMGCS1." (PMID 28962550, 2017). "Against this background, we analyzed the expression of the anti-apoptotic BCL-2 family members BCL-2, BCL-XL and MCL-1 in our cancer models with conditional pathway activation." (PMID 28507280, 2017). "Platycodin D has significantly reduced the Bcl‐2/Bax ratio and increased the expression of cleaved caspase‐9, caspase‐3 and PARP in PC‐3, AGS, HepG2 and MCF‐7 cancer cells." (PMID 26648178, 2016). "In particular, in normal and cancer cell, BCN1/BCL2 complexes can be disrupted by NIX/BNIP3L, which bind to BCL-2 proteins and subsequently activate the autophagy initiation complex." (PMID 27326761, 2016). "Small molecules that antagonize pro-survival Bcl-2 proteins, namely BH3 mimetics, are currently under pre-clinical and clinical evaluation as single agent anti-cancer therapies and as sensitizers to apoptosis-inducing drugs." (PMID 27494880, 2016).
cancer (continued). "TUG1 regulated the cancer genes ACVR1B and BCL2 in KIRC, while it competitively regulated PPARG in BLCA." (PMID 27580177, 2016). "We validated bcl-2/SLIRP interaction by immunoprecipitation and immunofluorescence experiments in cancer cell lines from different histotypes." (PMID 26866271, 2016). "In cancer cells, as the nuclear retention of AUF1 is increased, cytoplasmic AUF1 levels decrease significantly, and as a result more Bcl-2 protein is produced." (PMID 27578251, 2016). "Recent identification of cell-permeable, selective inhibitors of BCL-2, BCL-XL and MCL-1, further facilitates the determination of the BCL-2 family dependency of cancer cells." (PMID 26954718, 2016). "Cardone and co‐workers showed that Cardone compound 9 had high activity in a panel of human derived cancer cell lines, in particular Mcl1‐1780 (EC50=0.3 μm), Bcl2‐1863 (EC50=1.1 μm), NCI‐H929 (EC50=1.6 μm) and SUDHL‐6 (EC50=3.3 μm)." (PMID 26696548, 2016). "MiR-15a/16-1 cluster within 0.5 kb at chromosome position 13q14 target several oncogenes (including BCL2, CCNE1 and CCNB1, which also existed in the two networks), to suppress cell cycle progression and proliferation in several malignant tumors." (PMID 27966444, 2016). "Cancer cells often exhibit higher levels of pro-apoptotic BH3-only protein, which is accompanied by higher anti-apoptotic BCL-2 proteins to antagonize apoptosis." (PMID 27455839, 2016). "The increase in cancer cell proliferation is mediated by STAT3-activated production of Bcl-xL, Bcl-2 and c-IAP2, which are also activated by NF-κB." (PMID 31051015, 2016). "The expression of CD133, ABCB1, Bcl-2, and ALDH1A1 in the fused cells explains the increased drug resistance of the fused cell, suggesting that the cancer cell would acquire drug resistance through cell fusion with the stem cell." (PMID 26846780, 2016). "To more fully assess the capacity of the designed inhibitors to determine BCL2 profiles, we tested them alongside existing, selective BH3-mimetics in a larger number of cell lines from one type of cancer." (PMID 27805565, 2016). "The functional roles of Bcl-2 were examined by MTS, flow cytometry and xenograft cancer mouse model." (PMID 27722045, 2016). "Messenger RNA data of lymphohematopoietic cancer lines suggest a correlation between expression of the cation channel TRPM2 and the antiapoptotic protein Bcl-2." (PMID 26839633, 2016). "FOSL1, BCL2, CDK6, IL7R, RUNX2 and CDC25B have been shown to be targets of JQ1 for transcriptional silencing in other types of cancers." (PMID 27764802, 2016). "In other cancer cell lines HepG2 and A549, ATF1 transcriptional activation of Bcl-2 was also impaired by knockdown of Pin1." (PMID 28032861, 2016). "Toward this end, we performed gene expression analysis of BCL-2 and BCL-xL in the Cancer Cell Line Encyclopedia." (PMID 26859456, 2016). "Anti-apoptotic BCL-2 family proteins, principally BCL-2, BCL-XL and MCL-1, maintain survival of cancer cells by sequestering their pro-apoptotic counterparts." (PMID 26954718, 2016). "Downregulation of Bcl-2 by using ABT-199, a potent and selective inhibitor of Bcl-2, has been shown to inhibit growth of a panel of cancers." (PMID 27722045, 2016). "Anti-mitotics-induced apoptosis is known to involve degradation of anti-apoptotic Bcl-2 proteins during mitotic arrest; however, it remains unclear how this mechanism accounts for significant heterogeneity observed in the cell death responses both within and between cancer cell types." (PMID 27811996, 2016). "Co-delivery to overcome the Bcl-2 mediated drug resistance during chemotherapy, enabling low-dose yet effective PTX treatment of cancer." (PMID 27786239, 2016).
cancer (continued). "Increased references in PubMed also provided us other hub proteins involved in cancer pathways, such as ESR1, PTEN, BCL2, AR and MAPK3." (PMID 27917343, 2016). "Expression of breast cancer 1 (BRCA1), breast cancer 2 (BRCA2), cathepsin D (CTSD), BCL2, and WISP2 were significantly increased." (PMID 27379522, 2016). "Suppression of FLI-1 inhibits cell proliferation and induces cell apoptosis of human cancer cell by targeting Rb, GATA-1, and BCL-2." (PMID 27304058, 2016). "The anti-apoptotic B-cell lymphoma 2 (BCL-2) family proteins, including BCL-2, BCL-XL, and MCL-1 have been characterized as key survival factors in multiple cancer types." (PMID 26134786, 2015). "The cytokine IL-24 can induce cancer cell apoptosis by activating caspase-9, caspase-3 and poly ADP-ribose polymerase (PARP) through downregulation of Bcl-2 expression and induction of cytochrome C release." (PMID 25895131, 2015). "Based upon the fact that the Bcl-2/Bax ratio plays a crucial role in cancer cell apoptosis, we reasoned that the reduction in Bcl-2/Bax ratio by TP/HCPT would allow less Bcl-2-Bax complex." (PMID 25573072, 2015). "UDCA also significantly changed the mRNA and protein expression of Bax, Bcl-2 and Bcl-xL in HSC-3 cancer cells." (PMID 25951128, 2015). "Immunohistochemistry analysis showed the down-regulation of PCNA and Bcl-2 proteins and the up-regulation of Bax protein after administration of EEAML compared with the cancer control group." (PMID 25860620, 2015). "This recently reported small molecule is more potent in inhibiting BCL-XL than navitoclax but shows negligible activity against BCL-2 or MCL-1, thus making it an excellent tool for dissecting BCL-XL cancer biology." (PMID 26134786, 2015). "Previous studies showed that NR4A1 in combination with p300 activated Sp-regulated genes such as survivin, bcl-2 and EGFR in cancer cells." (PMID 26035713, 2015). "The expression of the anti-apoptotic proteins BCL-2, BCL-xL, and MCL-1 is upregulated in many cancer types and these proteins, as pro-survival oncogenes, contribute to the uncontrolled proliferation." (PMID 26198850, 2015). "Twelve genes were frequently targeted in both cohorts independently, including BCL2, BCL6, BCL7A, CD74 and CIITA, all listed as oncogenes in the Cancer Gene Census and known to be involved in lymphomagenesis." (PMID 25903198, 2015). "Enriched genes also included factors involved in cancer pathways and PI3K/AKT signalling, including IRS1, BCL2, TGFB3 and FGF18." (PMID 26698305, 2015). "Quantitative real-time PCR assay on expression of Bcl-2, Survivin and Bax was performed to determine the effect of metformin at low dose on epithelial-mesenchymal transition (EMT) of cancer cells and CSCs." (PMID 26718286, 2015). "Previous studies showed that miR-34a targets the oncogenes CDK4, CDK6, CCND1, MET, and BCL2, whereas miR-497 targets the oncogenes CCND2 and BCL2 in various types of cancer." (PMID 25909221, 2015).
cancer (continued). "The over-expression of IPS-1 downregulated the anti-apoptotic genes such as BCL2, BIRC3 and PRKCE, known to promote survival in different types of cancer." (PMID 25950488, 2015). "Anti-apoptotic members of the family (such as BCL-2, BCL-XL, BCL-W and MCL-1), which are overexpressed in many cancers, function by sequestering the pro-apoptotic executioners of the MOMP (such as BAX and BAK)." (PMID 26230693, 2015). "Several target genes of miR-204, including HOXA10, MEIS1, FOXC1, MAP1LC3B, BCL2, NTRK2, SOX4 and EphB2, have been identified in different cancers." (PMID 26710269, 2015). "In Mitelman's database of cytogenetic alterations in cancer, 62% of DH/TH cases had MYC/BCL2 translocations." (PMID 26416427, 2015). "In addition, overexpression of the BCL-2 protein may contribute to metastasis in certain cancers." (PMID 25874209, 2015). "There, BCL-2 and BCL-XL suppress cell death and promote survival and growth of cancer cells by suppression of BAK/BAX-dependent pore formation during mitochondrial outer membrane permeabilization (MOMP)." (PMID 25328887, 2014). "Collectively, these findings suggest that the simultaneous downregulation of BCL-2 and BCL-xL is a rational strategy for the implementation of anti-cancer therapy." (PMID 24637737, 2014). "Combining Bcl-2-specific inhibitors (such as ABT-737 and HA14-1) with TRAIL would be a powerful strategy against cancer." (PMID 24765133, 2014). "MiR-196b-5p is dysregulated in many malignancies, has been related to cancer prognosis, and targets c-myc, ERG, MEIS1, FAS, ABL1, BCL-2 and several HOX genes." (PMID 25329796, 2014). "Previous studies have also shown that curcumin can induce apoptosis in many types of cancer cells, through the inhibition of NF-κB, survivin/BIRC5, and BCL-2." (PMID 24999473, 2014). "These particles proved to be efficiently internalized by cancer cells and selectively knockdown GAPDH and Bcl-2 expression at both the protein and mRNA levels." (PMID 25229941, 2014). "Using next-generation sequencing, MCL1 has been identified as the most amplified gene in a screen of 3,000 individual cancers, highlighting its importance for cancer and suggesting a unique function of MCL1 amongst the antiapoptotic BCL2-proteins." (PMID 26556430, 2014). "Over-expression of anti-apoptotic BCL2 family proteins, such as BCL2, BCL-XL, MCL1 and BCL2A1, has been observed in many types of cancer including MB." (PMID 24887326, 2014). "If the Bcl-2's inhibitory action on IP3R is reversed, pro-apoptotic Ca2+ signaling will be triggered in cancer-B cells." (PMID 25430556, 2014). "In several cancer cell lines, it has been shown that NVP-BEZ235 induced apoptosis and cell cycle arrest accompanied by increased caspase 3 activity, and bcl-2 abrogated the effects of NVP-BEZ235." (PMID 24498161, 2014). "In various cancers, including OSCC, high expression of Bcl-2 and low expression of PUMA were important characteristics." (PMID 25474084, 2014). "Gos is a natural BH3 mimetics, acting as a small molecule inhibitor for the interaction between anti-apoptotic Bcl-2/Bcl-XL/Mcl-1 and pro-apoptotic BH3-only proteins such as BIM, BID, BAD or BIK, thereby induces apoptosis in cancer cells." (PMID 25231749, 2014). "Although ABT-737, a small-molecule Bcl-2/Bcl-xL inhibitor, has recently emerged as a novel cancer therapeutic agent, ABT-737-induced apoptosis is often blocked in several types of cancer cells with elevated expression of Mcl-1." (PMID 25375379, 2014).